RLN2 (relaxin 2)
Description:
Relaxin is an ovarian hormone that acts with estrogen to produce dilatation of the birth canal in many mammals. May be involved in remodeling of connective tissues during pregnancy, promoting growth of pubic ligaments and ripening of the cervix.
Synonyms: H2; RLXH2; bA12D24.1.1; bA12D24.1.2; H2-RLX
Tractability: Antibody: its Gene Ontology location is reachable by antibodies, with high confidence; UniProt places it where antibodies can reach, with medium confidence; UniProt predicts a signal peptide or a membrane-spanning region.
Gene: Protein-coding gene on chromosome 9 (5,299,864 to 5,304,716, reverse strand). Ensembl gene ENSG00000107014.
Subcellular location: Secreted
Pathways (Reactome):
Signal Transduction: G alpha (s) signalling events; Relaxin receptors
Gene Ontology:
Molecular function: hormone activity
Biological process: positive regulation of angiogenesis; positive regulation of gene expression; regulation of catalytic activity; female pregnancy; signal transduction
Cellular component: extracellular region
Genetic constraint (gnomAD): Loss-of-function variants: 5 observed, 5.18 expected, observed/expected ratio (o/e) 0.97, 90% interval 0.5 to 1.78. That is too few expected variants to judge how well the gene tolerates losing a copy. Missense variants: 286 observed, 216.9 expected, observed/expected ratio (o/e) 1.32, 90% interval 1.2 to 1.45. Synonymous variants: 101 observed, 85.24 expected, observed/expected ratio (o/e) 1.18, 90% interval 1.01 to 1.4.
Homologues: Orthologues: chimpanzee RLN2 (97% identical), macaque RLN2 (83% identical), mouse Rln1 (47% identical), rat Rln1 (46% identical), rabbit RLN1 (42% identical), dog RLN2 (41% identical). Paralogues in human: RLN1 (82% identical), INSL4 (24% identical), INSL6 (24% identical).
Diseases named in the same sentence as RLN2 in open-access papers:
RLN2 is named in the same sentence as 59 diseases in open-access papers, as found by Europe PMC text mining. Sharing a sentence is not in itself a finding about the gene and the disease. The quoted sentences say what the papers report.
prostate carcinoma (9 papers, 2013 to 2025). A carcinoma that arises from epithelial cells of the prostate gland. "In some cancers, such as prostate cancer, RLN2 has been shown to activate the Wnt pathway, promoting tumor cell proliferation and survival." (PMID 41373753, 2025). "In previous reports using RLN2-overexpressing prostate cancer xenograft models, an increased number of vascular endothelial cells expressing factor VIII was observed in tumor tissues." (PMID 40666525, 2025). "Concerning the normal prostate epithelial cell line, PNT1A, there was similar effect of Ang II and RLN2 as in prostate cancer cell lines." (PMID 33673178, 2021). "RLN1 is known to form a fusion with RLN2 in LNCaP cells as well as in normal and prostate cancer tissues." (PMID 31303963, 2019). "RXFP1-dependent and RLN2-induced proliferation of prostate carcinoma cells was mediated via a PI3K/Akt signaling pathway." (PMID 26322020, 2015). "This ΔH2 mutant was able to bind to RXFP1 and function as a partial antagonist to functional RLN2 in an in vivo xenograft model of prostate cancer." (PMID 26322020, 2015). "The siRNA-mediated knockdown of RXFP1 prevented the RLN2-induced increase in prostate cancer cell proliferation and invasiveness and induced apoptosis." (PMID 26322020, 2015). "In xenografts of relaxin-2-overexpressing prostate cancer cell lines, tumour growth and neoangiogenesis are significantly enhanced." (PMID 23963762, 2014). "Increased production of relaxin-2 as well as relaxin by tumour and stromal cells has been demonstrated in advanced prostate cancers in humans and mice." (PMID 23963762, 2014). "The lentiviral delivery of relaxin-2 into PC-3 prostate cancer cells increases xenograft tumor growth." (PMID 23758748, 2013). "However, elevated RLN2 levels have been reported in other cancers, such as prostate cancer, breast cancer, and osteosarcoma, where they correlate with disease progression and poorer prognosis, which prompted us to conduct research on this parameter." (PMID 41373753, 2025). "Ang II and relaxin 2 can modulate expression of androgen receptors (ARs) in prostate cancer cells." (PMID 33673178, 2021). "To test whether prostate cancer cells turn off gene expression by switching between utilisation of promoters that generate coding and noncoding mRNAs, we analysed RLN2 protein levels." (PMID 30271587, 2018). "In prostate cancer, RLN2/RXFP1 signaling increased cell migration and proliferation in androgen-receptor (AR)-dependent LNCaP and AR-independent PC3 prostate cancer cells and promoted growth in xenografts derived of androgen-independent PC3 prostate cancer cells." (PMID 26322020, 2015). "Certainly, inhibition of RLN2 and/or its receptor RXFP1 in prostate cancer cells has been shown to inhibit metastasis and invasiveness in vitro." (PMID 41373753, 2025). "In two prostate cancer cell lines, LNCaP (high androgen receptor activity, low invasiveness) and PC3 (low androgen receptor activity, highly metastatic), both peptides, Ang II and relaxin 2, induced proliferation, however, greater changes were observed in androgen-dependent cell line." (PMID 33673178, 2021).
osteosarcoma (7 papers, 2013 to 2025). A usually aggressive malignant bone-forming mesenchymal neoplasm, predominantly affecting adolescents and young adults. "Relaxin-2 has mostly been implicated in tumors that metastasize to bone, such as breast, prostate, and thyroid cancers, and myeloma, but it has also been associated with primary osteosarcoma." (PMID 35562926, 2022). "However, the observed differences in median values suggest a possible elevation of this parameter, similar to what has been reported in other cancers, such as prostate, breast, ovarian, and osteosarcoma, where higher RLN2 levels were associated with advanced disease and poorer prognosis." (PMID 41373753, 2025). "Relaxin-2 (RLN2) increases osteosarcoma cell migration, invasiveness, proliferation, and participates in the activation of the S100A4/MMP-9 signaling." (PMID 29069865, 2017). "The aim of the study was to determine the effect of H2 relaxin (RLN2) on invasion, migration, and chemosensitivity to cisplatin in human osteosarcoma U2-OS and MG-63 cells and then to investigate the effect of RLN2 on the AKT/NF-κB signaling pathway." (PMID 26229955, 2015). "Real-time quantitative RT-PCR assay was performed to detect the expression of relaxin-2 mRNA in 36 cases of human osteosarcoma tissue samples." (PMID 23758748, 2013). "Our results demonstrate that relaxin-2 serum concentrations in a population of osteosarcoma patients yielded significantly higher relaxin-2 concentrations than in a control group of healthy blood donors." (PMID 23758748, 2013). "Relaxin-2 protein and mRNA was examined in 3 human osteosarcoma cell lines MG-63, U-2OS and Saos-2 by western-blot and QRT-PCR." (PMID 23758748, 2013). "Serum relaxin-2 levels was measured in ELISA-based method in the 36 cases of osteosarcoma and 50 cases of controls." (PMID 23758748, 2013). "Our study suggests that aberrant expression of relaxin-2 is critical for the development of human osteosarcoma, and relaxin-2 is the better target gene for treatment of osteosarcoma." (PMID 23758748, 2013). "ELISA assay was performed to detect the serum relaxin-2 levels in 36 osteosarcoma patients and 50 controls." (PMID 23758748, 2013). "We next investigated the role of relaxin-2 in osteosarcoma by means of relaxin-2 knockdown with siRNA." (PMID 23758748, 2013). "Our study suggests that overexpression of relaxin-2 is critical for the metastasis of human osteosarcoma." (PMID 23758748, 2013). "We therefore suggest that RLN2 could regulate osteosarcoma invasion, which might be through AKT/NF-κB (MMPs and VEGF) signal pathway." (PMID 26229955, 2015). "We therefore suggested that the expression of relaxin-2 mRNA in osteosarcoma tissues or relaxin-2 serum concentrations in a population of osteosarcoma patients may serve as a new prognostic predictor for osteosarcoma." (PMID 23758748, 2013). "We therefore suggested that relaxin-2 may be as a potential therapeutic targets for osteosarcoma treatment." (PMID 23758748, 2013). "We then studied the effect of inhibition of relaxin-2 on osteosarcoma cells in vivo mice modes." (PMID 23758748, 2013). "The results showed the levels of relaxin-2 mRNA expression in osteosarcoma tissue samples were significantly higher than those in the corresponding non-tumor tissue samples (P < 0.01), and the serum relaxin-2 levels were significantly higher in OS patients than in healthy controls (P < 0.01)." (PMID 23758748, 2013). "Relaxin-2 may be the better target gene for treatment of osteosarcoma." (PMID 23758748, 2013). "The aim of this study was to clarify the clinicopathological outcome of serum relaxin-2 and tissues relaxin-2 expression levels in human primary osteosarcoma (OS), and to explore the roles of relaxin-2 inhibition and determine its possibility as a therapeutic target in human osteosarcoma." (PMID 23758748, 2013). "However, the mechanisms of relaxin-2 effects in osteosarcoma cells remain to be further elucidated." (PMID 23758748, 2013).
osteosarcoma (continued). "Furthermore, relaxin-2 is the potential molecular target for osteosarcoma therapy." (PMID 23758748, 2013). "Thus, we conclude that relaxin-2 may play important roles in osteosarcoma development and metastasis, which is also consistent with previous reports in other malignancies." (PMID 23758748, 2013). "In addition, the serum RLN2 or relaxin level has been well examined and is reported to have some benefit as a predictive marker for malignant features, such as metastasis, and for prognosis for several types of cancer, including prostate, ovarian, esophageal, breast, and osteosarcoma." (PMID 30126180, 2018). "The levels of relaxin-2 mRNA expression in osteosarcoma tissue samples were significantly higher than those in the corresponding non-tumor tissue samples, which showed no or very low levels of relaxin-2 mRNA expression." (PMID 23758748, 2013). "Real-time quantitative RT-PCR assay was performed to detect the expression of relaxin-2 mRNA in osteosarcoma tissues or corresponding non-tumor tissues from 36 osteosarcoma patients." (PMID 23758748, 2013). "In the present study, we found that the expression of relaxin-2 mRNA were significantly higher in osteosarcoma tissue samples than those in corresponding non-tumor tissue samples." (PMID 23758748, 2013).
heart failure (5 papers, 2015 to 2024). Inability of the heart to pump blood at an adequate rate to meet tissue metabolic requirements. "Its ability to activate cellular responsessuch as vasodilation, angiogenesis, and anti-inflammatory and antifibroticeffects has led to significant interest in using relaxin-2 as a therapeuticfor heart failure and several fibrotic conditions." (PMID 39134056, 2024). "Serelaxin, recombinant human relaxin-2, has recently been found to improve the prognosis in patients with heart failure." (PMID 26446052, 2015). "This review provides an overview of serelaxin use in clinical trials and discusses future directions in the development of relaxin-2 mimetics, which may offer new therapeutic options for patients with heart failure." (PMID 37721595, 2024). "The role of relaxin-2, or its recombinant human form known as serelaxin, has been investigated in preclinical and clinical studies as a potential therapy for cardiovascular diseases, especially heart failure, whose current therapy is still unoptimized." (PMID 37721595, 2024). "Relaxin-2 exerts many favourable cardiovascular effects in pathological circumstances such as atrial fibrillation (AF) and heart failure, but the mechanisms underlying its actions are not completely understood." (PMID 36566255, 2022). "Recent preclinical and clinical outcomes have encouraged the potential use of relaxin-2 (or its recombinant form, known as serelaxin) as a therapeutic strategy during cardiac injury and/or in patients suffering from different cardiovascular disarrangements, especially heart failure." (PMID 35887517, 2022).
breast carcinoma (4 papers, 2014 to 2025). "The effects of RLN2 on MMP expression have previously been reported in breast cancer and glioblastoma cell lines." (PMID 40666525, 2025). "In breast cancer, RLN2 produced by tumor-infiltrating neutrophils (TANs) has been shown to stimulate tumor cell migration by activating the G-CSF-RLN2-MMP-9 axis, leading to increased invasiveness and metastatic potential." (PMID 41373753, 2025). "Elevated circulating levels of RLN2 were also found in patients with breast cancer." (PMID 41373753, 2025). "In vivo, we could show that elevated relaxin-2 serum levels in breast cancer patients correlate with metastatic disease and high RXFP1 mRNA levels are an independent marker of metastasis and shortened survival in dogs." (PMID 23963762, 2014). "In breast cancer cells such as MCF-7, RLN2 has been primarily shown to induce NO production by upregulating inducible nitric oxide synthase (iNOS), possibly to promote increased blood flow and angiogenesis in these cells." (PMID 41373753, 2025).
liver fibrosis (4 papers, 2017 to 2026). "In this study, we demonstrate that circRNAs encoding human relaxin-2 represent a new and effective therapeutic strategy for liver fibrosis." (PMID 41552388, 2026). "Here, we report the development of a circRNA encoding human relaxin-2 (cRLN2), a short peptide hormone with well-established therapeutic potential, to treat liver fibrosis in a mouse model." (PMID 41552388, 2026). "Collectively, these results indicated that human relaxin-2 can exert similar biological functions as murine relaxin-1 in mice to effectively alleviate liver fibrosis." (PMID 41552388, 2026). "In this study, we engineered circRNA encoding human relaxin-2, which can be translated into cells via the CVB3 IRES to produce active proteins that may potentially exert therapeutic effects for liver fibrosis." (PMID 41552388, 2026). "Although the efficacy of RLN2 in acute heart failure has not been confirmed, various preclinical studies have confirmed its promising antifibrotic effects in fibrosis-related diseases, such as hypertrophic cardiomyopathy, hepatic fibrosis, and renal fibrosis." (PMID 40666525, 2025).
acute myocardial infarction (3 papers, 2018 to 2022). Necrosis of the myocardium, as a result of interruption of the blood supply to the area. "The 72-h intravenous administration of rh-relaxin-2 in acute myocardial infarction resulted in early beneficial effects, including reduced inflammation." (PMID 32859236, 2020). "On the other hand, one recent study demonstrated that recombinant human relaxin-2 (serelaxin) inhibited myocardial infarction following ischemia-reperfusion injury by eNOS activation, while eNOS deletion abolished serelaxin's beneficial effects." (PMID 29636838, 2018).
atrial fibrillation (3 papers, 2022 to 2023). A disorder characterized by an electrocardiographic finding of a supraventricular arrhythmia characterized by the replacement of consistent P waves by rapid oscillations or fibrillatory waves that vary in size, shape and timing and are accompanied by an irregular ventricular response. "In pathological conditions like AF (atrial fibrillation) and cardiac failure, relaxin-2 has several beneficial cardiovascular benefits, although the exact processes by which it works are still poorly known." (PMID 37900385, 2023).
chronic kidney disease (2 papers, 2023 to 2025). Impairment of the renal function secondary to chronic kidney damage persisting for three or more months. "Therefore, relaxin-2 mRNA exhibits potential as a novel therapy for inhibiting fibrosis and inflammation in chronic kidney disease." (PMID 37545557, 2023). "Therefore, we speculate that therapeutic administration of relaxin-2 mRNA has potential for suppressing the progression of chronic kidney disease (CKD) in patients, since many of the pathomechanisms seen in the UUO model also appear in patients with progressive CKD." (PMID 37545557, 2023).
endometrial cancer (2 papers, 2018 to 2019). Primary or metastatic malignant neoplasm involving the endometrium (mucous membrane that lines the endometrial cavity). "An important hallmark to use in the differential diagnosis of RLN2-induced invasive endometrial cancer is β-catenin phosphorylation via RXFP1 and a weakening of the adherens junctions through breakage of the cadherin/catenin complex." (PMID 30126180, 2018). "In our study, RLN2 immunoreactivity was marginally associated with histological grade in endometrial carcinoma cases." (PMID 30126180, 2018). "Relaxin 2/RXFP1 Signalling induces cell invasion via the beta-catenin pathway in endometrial cancer." (PMID 31886214, 2019). "Further examination regarding the expression of invasiveness-related factors will be required to clarify the mechanisms of invasion in RLN2-treated human endometrial cancer cells." (PMID 30126180, 2018). "This suggests that RLN2 is a potent signal for β-catenin phosphorylation via RXFP1 binding in endometrial cancer cells." (PMID 30126180, 2018). "Future studies will require clarifying the role of RLN2 and its receptor signaling in endometrial cancer cells." (PMID 30126180, 2018). "This is the first study addressing RLN2-induced cellular invasion through RXFP1 signal transduction, β-catenin phosphorylation, and loss of E-cadherin in in vitro endometrial cancer cells." (PMID 30126180, 2018). "Further examination regarding the correlation between the serum or intratumoral RLN2 concentration and the immunohistochemical status of RLN2 is necessary to use RLA2 evaluation for clinical predictions or as a prognostic marker for endometrial cancer." (PMID 30126180, 2018). "It was previously reported that RLN2 immunoreactivity was positively correlated with histological grade and myometrial invasion in tissue microarray samples from 57 endometrial cancer cases." (PMID 30126180, 2018). "RLN2 immunoreactivity was detected in the human endometrial carcinoma cells and had a correlative tendency with histological grade and RXFP1." (PMID 30126180, 2018). "In this study, we examined the effects of relaxin 2 (RLN2), the major circulating relaxin in humans, on human endometrial carcinoma cell lines." (PMID 30126180, 2018). "Therefore, in this study, we first examined the effects of RLN2 on Ishikawa and HEC-1B human endometrial cancer cell line invasiveness." (PMID 30126180, 2018).